CDK5 (cyclin dependent kinase 5)
Diseases named in the same sentence as CDK5 in open-access papers (continued):
Sharing a sentence is not in itself a finding about the gene and the disease.
pancreatic cancer (continued). "The roles of Cdk5 in pancreatic cancer formation and progression via Ras-Ral signaling have been further proven by rescue test, in which constitutively activating RalA-GTP and RalB-GTP in pancreatic cancer cells expressing dominant-negative Cdk5 significantly rescued the effects of Cdk5 inhibition." (PMID 28288624, 2017). "The usage of shRNA technology or inhibitors to block the expression of CDK5 in pancreatic cancer cells could dramatically inhibit the growth of MIApaCa-2 cells, thereby reducing the incidence of tumor development." (PMID 27406233, 2016). "Furthermore, CDK5 is also hyperactivated in pancreatic cancer due to mutant K-Ras." (PMID 37993880, 2023). "However, as the vast majority of pancreatic tumors overexpress CDK5, p35 and p39, the contribution of p25 to disease pathogenesis remains unclear." (PMID 37993880, 2023). "Therefore, the development of CDK5 and Notch as combinational targets for pancreatic cancer could be undertaken." (PMID 33960694, 2021). "Another recent study has reported that CDK5-mediated T261-EZH2 phosphorylation facilitates FBW7-mediated EZH2 ubiquitination and proteasome degradation in pancreatic cancer cells." (PMID 33308321, 2020). "Thus, we examined whether CDK5 regulates PES1 in pancreatic cancer." (PMID 31718704, 2019). "For instance, dinaciclib is an inhibitor of CDK1, CDK2, CDK5, and CDK9, and is active in a broad range of cancer cell lines originating from leukemia, melanoma, osteosarcoma and pancreatic cancer." (PMID 31446060, 2019). "Finally, CDK5 phosphorylated and stabilized PES1, and Dinaciclib was proven to down-regulate PES1 and overcome pancreatic cancer cell resistance to JQ1." (PMID 31718704, 2019). "Then, the knockdown of CDK5 decreased the protein expression levels of PES1 but not mRNA levels in pancreatic cancer cells, consistent with the results obtained after Dinaciclib treatment." (PMID 31718704, 2019). "Finally, CDK5 inhibitors were proven to destabilize PES1 and overcome cancer cell resistance to BET inhibitors in pancreatic cancer cells." (PMID 31718704, 2019). "Finally, we assess CDK5 inhibitors’ ability to destabilize the PES1 protein and overcome cancer cell resistance to BET inhibitors in pancreatic cancer." (PMID 31718704, 2019). "CDK5 signaling, NRF2-mediated oxidative stress response, glucocorticoid signaling, and ERK/MAPK signaling were among most prominent signaling pathways modulating the growth inhibitory effects of fisetin on hepatic and pancreatic cancer cells." (PMID 28052097, 2017). "Although the exact molecular mechanism was not delineated, CDK5 may regulate the activation of RalA and RalB by controlling the function of either RalGEFs or RalGAP, suggesting CDK5 as a possible target for pancreatic cancer." (PMID 37993880, 2023).
Stroke (22 papers, 2010 to 2025). Sudden impairment of blood flow to a part of the brain due to occlusion or rupture of an artery to the brain. "Cyclin-dependent kinase 5 (CDK5) is a kind of proline-directed serine/threonine kinase and the overactivation of CDK5 has been implicated in neuronal cell death in stroke." (PMID 37480049, 2023). "This pathway was previously shown to be a key initiator of cellular apoptosis following stroke, associated with excitotoxic release of calpains and subsequent hyper-phosphorylation of the CDK5 protein following p35 conversion to p25." (PMID 32378028, 2021). "Targeting aberrant CDK5 is neuroprotective for the neuronal loss, tauopathy, and microglial hyperreactivity induced by stroke." (PMID 31595208, 2019). "We conclude that zinc-induced CDK5-Tyr15 phosphorylation underlies CDK5 activation and promotes ischemic neuronal death in stroke." (PMID 30158515, 2018). "Aberrant CDK5 activation has been identified to be a principal cause of neuronal death during stroke." (PMID 30158515, 2018). "All these findings support that zinc-induced CDK5-Tyr15 phosphorylation underlies CDK5 activation and promotes ischemic neuronal death in stroke." (PMID 30158515, 2018). "Roscovitine, an inhibitor of CDK5 with additional immunosuppressive effects reduced neuronal loss, glial activation, as well as microglia proliferation, NO release, and neurologic deficits after brain trauma or stroke." (PMID 35572146, 2022). "The aberrant activation of CDK5 has been implicated in neuronal death in stroke." (PMID 31595208, 2019). "One discrepancy between previous studies and our work is the directionality of Cdk5 activity changes with stroke." (PMID 38480905, 2024). "PSD-located CaMKII, PKC, and Cdk5 activities were decreased while Pyk2 activity was increased after stroke." (PMID 38480905, 2024). "While constitutive Cdk5 knockout is perinatally lethal, conditional knockout mice display resilience to stress-induction, enhanced cognition, neuroprotection from stroke and head trauma, and ameliorated neurodegeneration." (PMID 35645825, 2022). "Cdk5 controls multiple cellular events in postmitotic neurons and participates in neuronal diseases, including stroke and neurodegenerative diseases." (PMID 35811833, 2022). "Here, we demonstrate that the application of the Tat-CDK5-CTM peptide, which can effectively disrupt the binding of CDK5 with NR2B and lead to the lysosomal-mediated degradation of CDK5, is protective against stroke damage both in vitro and in vivo." (PMID 31595208, 2019). "Some researchers have reported that roscovitine can protect neurons in models of spinal ischemic damage, stroke, and traumatic brain injury, showing that roscovitine can significantly decrease the expression of Cdk5/p25 complex." (PMID 31506563, 2019). "Compared to stroke animals, rats receiving hypothermia therapy had a lower p-CDK5 level, indicating that hypothermia suppressed the activation of the CDK5 signaling pathway, consequently decreasing IL-1β generation." (PMID 31644666, 2019). "The peptide-directed lysosomal degradation of CDK5 is a promising therapeutic intervention for stroke." (PMID 31595208, 2019). "CDK5 activation promotes ischemic neuronal death in stroke, with the recognized activation mechanism being calpain-dependent p35 cleavage to p25." (PMID 30158515, 2018). "Our data suggest that zinc-induced CDK5-Tyr15 phosphorylation promotes CDK5 activation and the following ischemic neuronal death in stroke." (PMID 30158515, 2018). "For example, viral-mediated dominant negative CDK5 expression was shown to inhibit death induced by hypoxia in a mouse stroke model." (PMID 26042811, 2015). "Increased expression of Cdk5 and of both p35 and p25 activators has been reported in human stroke and after focal middle cerebral artery occlusion." (PMID 24098701, 2013).
Stroke (continued). "Cyclin-dependent kinase-5 (Cdk5) is over-expressed in both neurons and microvessels in hypoxic regions of stroke tissue and has a significant pathological role following hyper-phosphorylation leading to calpain-induced cell death." (PMID 24098701, 2013). "We also show that (S)-roscovitine regulates CDK5 in vivo activity after stroke, suggesting that CDK5 is involved in (S)-roscovitine in vivo beneficial effect on ischemic brain." (PMID 20711428, 2010). "Multiple synthetic inhibitors that affect Cdk5 activity (such as roscovitine, olomoleucine, and purvalanol-A) have been discovered and proven to exert neuroprotective effects in preclinical research on stroke and TBI12." (PMID 38200156, 2024). "It has been reported that abnormal CDK5 activation is involved in the pathogenesis of stroke." (PMID 35501719, 2022). "Therefore, proteins that control microtubular mounts (e.g., glycogen kinase 3 (GSK3) and cyclin-dependent kinase 5 (CDK5)) and remodelling of the actin cytoskeleton can be potential targets for neuroregeneration following stroke." (PMID 33924191, 2021). "The goal of this study is to determine whether knocking down CDK5 by a peptide-directed lysosomal degradation approach is therapeutically effective against stroke." (PMID 31595208, 2019). "Increased CDK5 protein levels or activities were detected in stroke animal models or patients." (PMID 30158515, 2018). "However, p25 accumulation is a common change in all stroke models, suggesting that p25 contributes to CDK5 activation in ischemic injury." (PMID 30158515, 2018). "Thus, an early intervention of [Zn2+]i rises and CDK5-Tyr15 phosphorylation is a promising therapeutic strategy in the treatment of stroke." (PMID 30158515, 2018). "Therefore, targeting the upstream factors inducing aberrant CDK5 activation in ischemic brain injury is a therapeutic strategy in stroke patients." (PMID 30158515, 2018). "Next, we explored the effect of chelatable Zn2+ in regulating CDK5 in stroke." (PMID 30158515, 2018). "In addition, recent studies show that overactivation of CDK5 is a crucially prodeath signal in stroke." (PMID 27651795, 2016). "CDK5 activity was next evaluated in our permanent mouse stroke model." (PMID 20711428, 2010). "Increasing evidence indisputably links cell cycle CDKs and CDK5 to the pathogenesis of stroke." (PMID 20711428, 2010). "Thus, we hypothesized that CDK5, which is abnormally activated after stroke, phosphorylates tau and mediates neuronal cell death." (PMID 35501719, 2022). "Thus, Tat-CDK5-CTM can protect against stroke damage in vivo." (PMID 31595208, 2019). "As a consequence, long-term inhibition of Cdk5 for stroke treatment may induce major side effects." (PMID 29581894, 2018). "Cdk5 and p35/p25 are concomitantly overexpressed in ECs in hypoxic regions of stroke tissue, suggesting that the balance of signaling between these pathways may help to define cellular fate in relation to angiogenesis or cell protection after stroke." (PMID 24098701, 2013). "In the microvasculature, circ-HIPK3 sponges miR-148b-3p, downregulating cyclin-dependent kinase 5 (CDK5) and CDK5 receptor 1 expression, which ultimately upregulates SIRT1 to promote post-stroke BMEC survival and mitochondrial function." (PMID 39598406, 2024). "More recent work using small-interfering peptides (SiPs) that selectively block Cdk5-p25 but not Cdk5-p35 interactions by both pharmacological and transgenic means has shown promise in preclinical models of neurodegeneration and stroke." (PMID 35645825, 2022).
Stroke (continued). "We also examined neuronal death by TUNEL and PI staining and found that Tat-CDK5-CTM reduced the percentage of TUNEL- or PI-positive cells when compared with vehicle- or Tat-s-CDK5-CTM-treated OGD neurons, suggesting that Tat-CDK5-CTM can protect against stroke damage in vitro." (PMID 31595208, 2019). "On the other side, CDK5 activation by Tyr15 phosphorylation was not investigated in stroke, even though it has been identified in numerous studies related to CDK5 activation in neurite and spine retraction, dendrite outgrowth and Abeta-triggered neurodegeneration." (PMID 30158515, 2018). "CIP is a derived-p35 cleavage peptide, which selectively targets Cdk5/p25 activity without affecting Cdk5/p35 signalling, suggesting that CIP may represent a novel selective vascular protector/stimulator in hypoxic conditions such as those encountered after stroke." (PMID 24098701, 2013).
epilepsy (19 papers, 2012 to 2024). A brain disorder characterized by episodes of abnormally increased neuronal discharge resulting in transient episodes of sensory or motor neurological dysfunction, or psychic dysfunction. "Downregulation of Cdk5 has been associated with attention deficit and hyperactivity disorder, epilepsy, and schizophrenia." (PMID 38542432, 2024). "Together, the progression of epilepsy‐impeded setup of synaptic proteins is close correlated with memory impairment in endothelial CDK5‐deficiency mice." (PMID 35770064, 2022). "Here, we found that mice with spontaneous epilepsy induced by endothelial CDK5 deficiency exhibited hippocampal‐dependent memory impairment at 6 months of age, but not at 2 months of age." (PMID 35770064, 2022). "Given that the Cdk5/p35 complex has been implicated in a variety of disorders, including epilepsy and AD, these findings are helpful in deciphering the purpose of the continued expression of these proteins in postnatal neurons." (PMID 29867369, 2018). "The mechanism of epilepsy in pericyte knockout Cdk5 mice may also be linked to decreased polar distribution of AQP4." (PMID 39479522, 2024). "Hence, AEDs exerted a therapeutic effect on vasogenic epilepsy derived from endothelial CDK5 loss, which results in downregulating epilepsy‐related Phka1 and Btaf1 and upregulating synaptic function‐related Grin1 and Magt1." (PMID 35770064, 2022). "Moreover, association between chronic loss of CDK5 and presence of seizures has been reported in other animal epilepsy models." (PMID 35686059, 2022). "Cdk5 rescued hippocampal synaptic plasticity in a mouse model of Fragile X Syndrome, a genetic form of intellectual disability associated with epilepsy, autism, and mood disorders, suggesting that activation of Cdk5 activity might be a pharmacological tool to treat Fragile X Syndrome." (PMID 38542432, 2024). "Recently, our previous studies have shown that brain endothelial CDK5 deletion induces progressive reactive astrogliosis and results in the development of spontaneous epilepsy in Cdh5‐CreERT2;CDK5f/f mice." (PMID 35770064, 2022). "In the present study, LoxP/Cre strategy was used to generate endothelial‐specific CDK5 knockout mice, and our data indicated that the mice exhibited spontaneous epilepsy accompanied by memory impairment at 6 months old." (PMID 35770064, 2022). "The underlying mechanisms of tau hyperphosphorylation in epilepsy involve alteration of tau kinases like glycogen synthase kinase-3β (GSK-3β) and cyclin-dependent kinase 5 (CDK5); overactivation of both has been detected in resected tissue from refractory patients with epilepsy." (PMID 39337715, 2024). "We generated a mouse model of spontaneous epilepsy by knocking out the Cdk5 gene in pericytes." (PMID 39479522, 2024). "The change of Cdk5/p35 expression in the hippocampus may play a role in epilepsy by affecting mossy fiber germination." (PMID 35966199, 2022). "However, more studies are still needed to unveil the role of Cdk5 in the pathophysiological process of epilepsy." (PMID 35966199, 2022). "Cdk5 naturally plays an important role in the pathological process of epilepsy." (PMID 35966199, 2022). "Indeed, activities of PKC and CDK5 are maintained or increased in the brain of epilepsy human patients and animal models." (PMID 33348808, 2020). "Endothelial-specific Cdk5 knockout increased CXCL1 expression and led to progressive astrogliosis in epilepsy." (PMID 37280283, 2023). "For example, the evidence linking Cdk5 to the functional organization of the AIS takes on added meaning in the light of recent data implicating the AIS in the pathology of Angelman syndrome and epilepsy." (PMID 25364642, 2012).
gastric cancer (18 papers, 2016 to 2025). A primary or metastatic malignant neoplasm involving the stomach. "Intriguingly, of these proapoptotic genes, CDK5 was shown to be deficient in gastric cancer and to suppress in vitro cancer cell proliferation and xenograft tumorigenesis in our previous study." (PMID 37990321, 2023). "In gastric cancer, low Cdk5 expression has been associated with adverse survival in 240 patient specimens." (PMID 32352232, 2020). "In gastric cancer CDK5 promotes apoptosis and sensitizes cells and mice to oxaliplatin through the stabilization of DP1 and activation of the E2F1 pathway." (PMID 39800748, 2025). "In gastric cancer, CDK5 is downregulated compared to healthy tissue, with its reduction correlating with increased cancer aggressiveness, lymph node metastasis, and lower five-year survival rates." (PMID 39800748, 2025). "The most striking example of Cdk5’s nuclear function is its paradoxical role as a tumor suppressor in gastric cancer." (PMID 41369365, 2025). "CDK5 has been specifically observed to be coexpressed with chromosomal maintenance 1 (CRM1) in gastric cancer, and this coexpression has been described as a promising prognostic model for gastric cancer." (PMID 36769170, 2023). "Together, these studies demonstrate that CDK5 acts as a tumor suppressor in gastric cancer, likely due to its nuclear localization." (PMID 37993880, 2023). "Functionally, cyclin-dependent kinase 5 (CDK5) promoted apoptosis of gastric cancer cells and sensitized cells and mice to oxaliplatin." (PMID 37990321, 2023). "In gastric cancer tissues, CDK5 levels are downregulated, and this downregulation is correlated with the severity of the disease as observed in lymph node metastases of gastric cancer." (PMID 36769170, 2023). "We found that overexpression of CDK5 significantly sensitized gastric cancer cells to oxaliplatin treatment, as indicated by reductions in the IC50 values." (PMID 37990321, 2023). "Given the results from the cytotoxicity assay and tumor xenograft model that showed the capacity of CDK5 to promote chemosensitivity, we investigated the clinical value of CDK5 in gastric cancer." (PMID 37990321, 2023). "In summary, these results indicate that CDK5 depletion predicts poor survival and chemoresistance in patients with gastric cancer." (PMID 37990321, 2023). "We propose an effective approach to reclassify gastric cancer into apoptotic phenotypes using transcriptomic data and discovered a CDK5-driven proapoptotic phenotype." (PMID 37990321, 2023). "In gastric cancer, CDK5 levels are generally significantly decreased, and CDK5 accumulation in the nucleus actually suppresses proliferation." (PMID 37377891, 2023). "To elucidate the downstream molecular mechanism of apoptosis regulated by CDK5 in gastric cancer, we performed GSEA in TCGA and several GEO cohorts by comparing CDK5-high-expression samples to CDK5-low-expression samples." (PMID 37990321, 2023). "When nuclear-targeted CDK5 was ectopically expressed in gastric cancer cells, it led to the inhibition of the proliferation of these cells in a xenograft model." (PMID 36769170, 2023). "Western blotting showed that transient overexpression of CDK5 obviously increased the expression of cleaved PARP and caspase 3 in gastric cancer cell lines, suggesting that intrinsic apoptosis is induced by CDK5." (PMID 37990321, 2023). "PP2A inhibition in cells stably expressing CDK5 showcased the opposite effects of CDK5-mediated inhibition of gastric cancer progression." (PMID 36769170, 2023). "CDK5 mostly acts as an oncogene, but in gastric cancer, it is a tumor suppressor due to its unique nuclear localization." (PMID 37993880, 2023). "Through DEG analysis of multiple phenotypes, we identified CDK5 as a novel proapoptotic gene in gastric cancer." (PMID 37990321, 2023). "CDK5 interacts with Protein phosphatase 2A (PP2A), which is downregulated in gastric cancer, and for which lower expression is associated with poor survival of the patients." (PMID 36769170, 2023).